LEP (leptin)
Diseases named in the same sentence as LEP in open-access papers (continued):
Sharing a sentence is not in itself a finding about the gene and the disease.
tumor (continued). "However, obesity-induced leptin and/or insulin resistance could thwart such tumor-suppressing activity by miR-4443 on TRAF4/NCOA1 and lead to potentiating the risks for CRC clinical presentation in obese individuals." (PMID 31007685, 2019). "Therefore, it is comprehensible that the presence of leptin in tumour microenvironment could play a substantial role by influencing a number of biological mechanisms such as inflammation, cellular proliferation, and evasion of apoptosis." (PMID 30510663, 2018). "Moreover, leptin autocrine and paracrine signaling loop found in PC cells could reinforce its effects on tumor development and PCSC, thus contributing to chemoresistance." (PMID 29719602, 2018). "Moreover, leptin may also directly activate the NF-κB pathway, which is notably involved in tumor progression and chemoresistance." (PMID 30366466, 2018). "However, early tumor onset was detected in mice implanted with leptin-treated tumorspheres." (PMID 27999190, 2017). "Thus, adiponectin mediates effects on tumor growth opposite to those of leptin." (PMID 28915700, 2017). "Furthermore, although adipose produces hundreds of adipokines, the ADIPO:LEP ratio may serve to indicate the contribution of adipose in creating a tumor growth microenvironment." (PMID 28676553, 2017). "These potent adipokines such as resistin, leptin, and adiponectin are involved in cell growth, proliferation, cell cycle control, and angiogenesis and could play a significant role in facilitating tumor growth and metastasis." (PMID 28168205, 2017). "In conclusion, our findings identify, for the first time, leptin as an important paracrine molecule that mediates the interaction between stromal cells and BCSCs, providing novel insights into understanding how BCSCs are influenced by the tumor microenvironment." (PMID 26556856, 2016). "Several studies indicated that adipose tissue itself is an endocrine organ that could influence tumour growth or differentiation via adipose tissue-derived hormones called adipocytokines, e.g., leptin, resistin, or adiponectin (ApN), most of which showed strong correlations with BMI." (PMID 26959740, 2016). "Moreover, we observed in tumour sections from LDFI-treated mice a marked decrease in the expression of the nuclear proliferation antigen Ki-67 as well as in the phosphorylation levels of leptin downstream effectors." (PMID 25721149, 2015). "In addition, they suggested that the tumour and surrounding adipose tissue promote a leptin-rich environment, which could contribute to tumour development." (PMID 26508818, 2015). "However, the molecular mechanisms underlying leptin-induced tumor progression have not been clearly elucidated." (PMID 25704884, 2015). "Thus, it emerges how leptin may play a crucial role in mediating malignant cell and tumor microenvironment interactions." (PMID 25505738, 2014). "In addition, the chronic elevation of CRP observed in obese subjects may potentiate leptin resistance, contributing to the carcinogenesis, tumor progression and poor outcomes of tumor patients." (PMID 24800842, 2014). "For this purpose, the impact of adipokines on the tumor invasion and angiogenesis process has, for the first time, been characterized by comparing leptin and adiponectin used at doses mimicking plasmatic levels of leptin and adiponectin similar to those of healthy or obese conditions." (PMID 23554900, 2013). "In addition, the inhibition of leptin-signaling results in diminished tumor growth and progression." (PMID 24176089, 2013). "However, more research is needed to establish the importance of leptin in tumor angiogenesis." (PMID 24202338, 2013). "This review is focused on updated information on how leptin could contribute to tumor angiogenesis." (PMID 24202338, 2013).
tumor (continued). "Among the genes participating in the cascade of signal transfer in cell activated by leptin, the following ones: AKT1, STAT3, MCL1 were qualified as differentiating stage I and II and VEGFC, CCNDI the encoding genes respectively as differentiating III and IV stage neoplasm." (PMID 22363883, 2011). "Indeed, one of the factors secreted by tumour and adipose cells is leptin, a small and pleiotropic cytokine, which could be involved in the regulation of tumour-related inflammatory response." (PMID 21139583, 2011). "It has been suggested that leptin may contribute to tumor growth." (PMID 21338489, 2011). "BAT within the mediastinum secretes adipokines such as leptin and pro‐inflammatory cytokines (e.g., IL‐6, TNF‐α), which promote tumor cell proliferation, angiogenesis, and immune evasion." (PMID 40755324, 2025). "On one hand, leptin promotes memory T cell exhaustion by enhancing PD‐1 expression through the STAT3 signaling pathway, thereby impairing anti‐tumor immunity." (PMID 41085102, 2025). "Excess white adipose tissue contributes to elevated levels of circulating free fatty acids and adipokines such as leptin, IL-6, and TNF-α, promoting a chronic inflammatory state that supports tumor progression." (PMID 40895542, 2025). "Leptin also acts as a pro-inflammatory adipokine that induces IL-6 and transforming growth factor β (TGF-β) overexpression and an oncoinflammatory tumor microenvironment development via JAK/STAT3, c-Jun, and Akt pathway activation." (PMID 40227577, 2025). "Leptin upregulated IRG1 in already polarized M2-like macrophages, and therefore exerted potential effects during later tumor stages." (PMID 40552282, 2025). "CAAs play an essential role in promoting tumor progression by secreting multiple adipokines, such as CCL2, CCL5, leptin, and adiponectin." (PMID 40248695, 2025). "Simultaneously, leptin-induced inflammatory signaling and adiponectin-suppressed AMPK pathway inactivation collectively promote tumor cell metabolic reprogramming, enhancing their adaptability to hypoxic microenvironments." (PMID 41164182, 2025). "Functioning additionally as a pro-angiogenic cytokine, leptin promotes the expression of VEGF and stimulates endothelial tube formation, driving neovascularisation in support of tumour expansion." (PMID 41586225, 2025). "WC reflects visceral fat, which is metabolically more active than subcutaneous fat and secretes pro-tumorigenic cytokines including leptin, TNF-α, and IL-6, all of which promote a pro-metastatic tumor microenvironment." (PMID 41139205, 2025). "Conversely, in pathological conditions such as leukemia, malignant cells can exploit normal signaling pathways (like leptin-JAK/STAT or CXCL12-CXCR4) to favor an adipocyte-rich, tumor-supportive niche." (PMID 40852589, 2025). "In addition, leptin may induce tumor cell growth through PI3K/Akt/mTOR pathway stimulation." (PMID 40227577, 2025). "Concurrently, altered adipokine signaling—characterized by elevated leptin and reduced adiponectin levels—exacerbates this process by enhancing pro-inflammatory and pro-fibrotic pathways, which may also contribute to a more aggressive tumor microenvironment and poorer oncologic outcomes." (PMID 41255618, 2025). "Leptin, as one of the most important adipokine, can promote the EMT of BC cells, thereby enhancing tumor metastasis, through the activation of the PI3K/AKT signaling pathway and the upregulation of pyruvate kinase M2 (PKM2)." (PMID 40248695, 2025). "To examine the effects of adipokines, particularly leptin, on ADAMTS13 regulation during tumor development, we employed the chorioallantoic membrane (CAM) xenograft model." (PMID 41211185, 2025). "Adipocyte-derived leptin also inhibits glycolysis in CD8+ lymphocytes by activation of the enzymes involved in FAO via the STAT3 pathway, impairing their anti-tumor activity." (PMID 40227577, 2025).
tumor (continued). "CAAs are better equipped to support tumor invasion and metastasis by releasing CCL2, CCL5, CXCL8, IL-6, leptin, adiponectin, and VEGF." (PMID 40076892, 2025). "Metabolic parameters, plasma biomarkers (including leptin, insulin, IGF-1, adiponectin, and estrone), mammary gland histology, tumor incidence, and gene expression profiles were longitudinally evaluated." (PMID 40806434, 2025). "In hormone-sensitive tissues, leptin interacts with insulin and IGF-1 signalling, forming an endocrine-oncogenic triad that supports tumour progression." (PMID 41586225, 2025). "The combined tumor markers CA19-9, CA125, leptin, thymidine kinase, CEA, CA15-3, and HE4 have been shown to have a 95% sensitivity and a 96% specificity for detecting EC." (PMID 40647541, 2025). "Upon binding to LepR, leptin activates the JAK2/STAT3 and PI3K/AKT signaling pathways, inducing tumor cell proliferation, EMT, and enhanced invasive capabilities." (PMID 41164182, 2025). "By binding to its receptor, leptin activates multiple signaling pathways, including the JAK/STAT, PI3K/AKT, and MAPK pathways, which directly promote tumor cell proliferation, survival, and angiogenesis." (PMID 41267926, 2025). "DCIS-like tumoroid can reduce adipocyte differentiation (PPAR-γ, AP2), decrease tumor-suppressor adipokine (adiponectin), and increase both adipocyte lipolysis (HSL) and tumor-enhancer adipokine (leptin) gene expression." (PMID 39072314, 2024). "The tumor cells recruit circulating hemocytes to the TME, triggering JNK activation, which subsequently induces cytokine Unpaired 2 (Upd2)/leptin expression that promotes secretion of Dilp2 from insulin-producing cells (IPCs)." (PMID 39642218, 2024). "In untreated and newly diagnosed patients with renal cell carcinoma, promoter methylation in the leptin gene (LEP), as well as leptin receptor gene (LEPR), is remarkably higher in tumor tissues compared with normal adjacent tissues." (PMID 38405061, 2024). "Leptin activates AKT by phosphorylation, thereby affecting macrophage polarization and inducing TAM-mediated tumor progression." (PMID 38611081, 2024). "Because FAO has been shown to promote tumor cell migration, we investigated FAO’s contribution to the leptin-induced migration in these two cell lines." (PMID 39609706, 2024). "Leptin interacts with inflammatory cytokines, such as VEGF and TGF-β, to establish and maintain an inflammatory immune state within the tumor microenvironment." (PMID 38571500, 2024). "Leptin is believed to exert a pro-migratory effect by activating the STAT and JAK signaling pathways, thereby influencing tumor progression." (PMID 38255203, 2024). "Evidence from preclinical studies is most supportive of tumor-modulating roles for insulin, CCK, and Lcn2, whereas data are less conclusive for the adipokines leptin and adiponectin, despite correlations from human epidemiologic studies." (PMID 37648285, 2023). "Receptors for leptin and adiponectin are upregulated in OGJ and correlate with the tumour stage and nodal involvement." (PMID 36790524, 2023). "CAAs increase the secretion of IL-6 and leptin, which activate the JAK/STAT3 axis in BC cells and reduce the sensitivity of tumor cells to the toxic effects of NKs." (PMID 36765683, 2023). "Adipose tissue releases more than 20 different types of adipokines, including leptin, adiponectin, TNF-α, and resistin, which can promote tumor growth, proliferation, and metastasis." (PMID 38137922, 2023). "Leptin-activated signaling and leptin-induced expression of target genes are inhibited by the nuclear Farnesoid X Receptor-(FXR), a tumor suppressor, through induction of the suppressor of the cytokine signaling 3 (SOCS3)." (PMID 37046676, 2023). "Leptin is another promising therapeutic target in the fight against CRC, a CAAs-derived adipokine that supports colorectal carcinogenesis and tumor progression." (PMID 37760840, 2023).
tumor (continued). "We earlier reported that Notch, IL-1α, leptin, and VEGF/VEGFR-2 expressions were higher in human CRC and tyroid tumor tissue compared to normal tissue." (PMID 38152619, 2023). "Notable differences in the expression of leptin (LEP) and IL-6 (IL6) were observed between tumor bulk from obese and lean patients in the NST ER+/HER2− subgroup." (PMID 37479706, 2023). "Increased levels of circulating leptin and exogenous lipids both drive immunosuppressive MDSC accumulation in adipose tissue and the TME, all of which work together to promote tumor growth." (PMID 35752704, 2022). "How leptin transits across the vasculature remains unclear, although it is intriguing to speculate that, for solid tumours such as SCCs, mechanical pressures might alter the vascular integrity and facilitate entry of circulating factors such as leptin into the tumour microenvironment." (PMID 36450983, 2022). "Noticeably, strong leptin expression was positively correlated with advanced primary tumor (T) stage and neck metastatic lymph node (N) stage in NPC tumor tissues." (PMID 35778755, 2022). "Since the report that physiological levels of leptin could control autophagy in multiple peripheral tissues, there has been increased interest in describing the effects of other adipokines secreted during obesity on tumor cell autophagy and their effect on tumor progression." (PMID 36291097, 2022). "Adipocytes produce several paracrine and endocrine factors known as adipocytokines, including leptin, adiponectin, tumor necrosis factor (TNF)-α and interleukin 6, potentially affecting tumor growth." (PMID 35233007, 2022). "The decrease of leptin and increase of leptin receptor in GLSECKO tumors was further confirmed by quantitative RT-PCR analyses on isolated tumor cells." (PMID 36381236, 2022). "As in humans, some biomarkers have been shown to promote tumor development in animal models, such as an increase in the concentrations of IGF-1, leptin, and sex hormones and a decrease in the concentration of adiponectin." (PMID 36262532, 2022). "In NSCLC sufferers, their serum and tumor samples comprised elevated quantities of STAT3-driven cytokines IL-6/11/22 and leptin and HGF growth factors." (PMID 36497125, 2022). "Hence, inhibition of the leptin-promoted STAT3/JAK signalling pathway may limit tumour metastasis." (PMID 35628118, 2022). "Four genes (IFNA1, IFNG, LEP, and PLG) were excluded from analysis because their PCR Ct values were greater than 32 for both tumor and control samples, indicating that the expression of these genes was extremely low and not reliable for comparison analysis." (PMID 35600354, 2022). "The proinflammatory state created by leptin and PPAT inflammation further creates suitable conditions for a more aggressive tumor characterized by a larger volume, higher grade, increased proliferative and invasive capacities." (PMID 35406450, 2022). "Adipocyte-derived leptin and IL-6 play key roles in the activation of the Jak/STAT and PI3K/Akt/mTOR pathways, which are frequently dysregulated in tumor pathogenesis." (PMID 35805003, 2022). "Leptin has also been shown to drive accumulation of myeloid-derived suppressor cells in the TME, which limit CTL activation and result in increased tumor burden." (PMID 35039633, 2022). "While associations did not vary by hormone receptor status, except for IL-8, heterogeneity by tumor size was observed for several biomarkers (IL-8, TNF-α, leptin, adiponectin)." (PMID 35948877, 2022). "Next, to explore the correlation between leptin expression and clinicopathological characteristics and the outcomes of patients with NPC, the intensities of IHC staining in NPC tumor tissues were divided into a high- or low- expression group." (PMID 35778755, 2022). "Leptin induces EMT by modulating the expression of EMT-related markers and promotes tumor metastasis." (PMID 35778755, 2022).
tumor (continued). "It was reported that adipocyte cells secreted leptin, TNF, IL-6, and adiponectin to induce a change in tumor gene expression related to angiogenesis signatures." (PMID 36014894, 2022). "However, IHC staining showed that the expression of leptin (an adipocyte marker) and α-SMA (a fibroblast marker) was marginally induced in the HFD-fed tumor xenografts, suggesting that circulating leptin may play a more vital role for the development of HFD-fed tumor xenografts." (PMID 34156978, 2021). "Leptin, in combination with adjacent adipocytes-derived fatty acids, trigger FAO to fuel tumor cell proliferation." (PMID 33535537, 2021). "In subsequent experiments, as expected, leptin also elevated ATP production and FAO level in tumor tissues while cotreatment with 3‐MA abrogated induction of ATP biogenesis and FAO by this leptin." (PMID 33226729, 2021). "Leptin can promote cell proliferation through MAPK signal pathway, and promote angiogenesis and tumor occurrence by up-regulating vascular endothelial growth factor, transforming growth factor-1 and basic fibroblast growth factor." (PMID 33468224, 2021). "LEP protein expression showed significant correlations with the tumor subtype (p = 0.001), LVI (p = 0.001), age of menarche (p = 0.01), tumor size (p = 0.01) and stage (p = 0.04)." (PMID 34884678, 2021). "The STAT3 role in leptin signaling is further attested by the fact that the inhibition of STAT3 had shown to promote cell cycle arrest, apoptosis and impede tumor invasion." (PMID 34588926, 2021). "EE is also known to suppress tumor growth by increasing the production of brain-derived neurotrophic factor (BDNF) in the hypothalamus, which reduces leptin production via sympathetic β-adrenergic receptors." (PMID 34745135, 2021). "We also investigated the correlation between leptin serum levels and leptin gene expression and CYP19 (aromatase) gene expression in corresponding tumor tissue specimens using whole genome sequencing (WGS) data." (PMID 34554372, 2021). "However, when the DIO mice were fed low-fat diets, body weight and the blood leptin level gradually decreased, and importantly, AdipoRon became effective in suppressing tumour growth, which was accompanied by increases in necrotic areas and decreases in Ki67-positive cells and tumour microvessels." (PMID 33536560, 2021). "Leptin can display angiogenic (at least partly by vascular endothelial growth factor (VEGF)) and mitogenic properties in the enhancement of tumor growth." (PMID 34068679, 2021). "In line with the in vitro findings, leptin administration upregulated precursor SREBP‐1 and induced SREBP‐1 maturation in tumor tissues, while cotreatment with 3‐MA prominently attenuated these changes." (PMID 33226729, 2021). "Leptin and PD-1 ligation in this setting increased STAT3 activity in tumor-infiltrating T cells, leading to decreased glycolysis and increased FAO." (PMID 33927722, 2021). "Leptin activates the MAPK and AKT pathways increasing the proliferation, angiogenesis and decreasing apoptosis in tumor cells." (PMID 34074045, 2021). "Staining for CADM3, IGLON5, and TGFB1 was low in tumor tissue; staining for LEP and ABI3BP was medium in tumor tissue; staining for CD1B was high in tumor tissue." (PMID 34497681, 2021). "In turn, HIF-1α is conducive to the adjustment of tumors to hypoxia through transcriptional activation of more than 100 downstream genes including LEP, EPO, PKM, etc.; in this regard, HIF-1α further promotes the proliferation of tumor cells." (PMID 33681184, 2020). "Tumor weight correlated positively with glucose (rs = 0.50, P < 0.001), HOMA-IR (rs = 0.45, P = 0.001), leptin (rs = 0.34, P = 0.017), and visfatin (rs = 0.49, P < 0.001) but is not correlated with insulin (rs = 0.26, P = 0.064)." (PMID 33381605, 2020). "The FXR agonist GW4064 induced a decrease in the activation of the leptin signaling pathway and reversed the CAF-induced effects on tumor progression and motility." (PMID 33006013, 2020).